ARF6 (ARF GTPase 6)
Diseases named in the same sentence as ARF6 in open-access papers (continued):
Sharing a sentence is not in itself a finding about the gene and the disease.
prostate carcinoma (11 papers, 2015 to 2024). A carcinoma that arises from epithelial cells of the prostate gland. "For example, the small GTPase ADP-ribosylation factor 6 (ARF6) has been implicated in prostate cancer invasion and metastasis by promoting matrix metalloproteinase (MMP) secretion and invadopodia formation." (PMID 39217195, 2024). "We examined the association of IQSEC1, ARF5, and ARF6 elevation with frequent genomic alterations in prostate cancer." (PMID 33712589, 2021). "Elevation in IQSEC1, ARF5 and ARF6 levels was associated with clinical outcome in prostate cancer across 12 studies, representing 2910 patients." (PMID 33712589, 2021). "The small GTPase ARF6 has been implicated in the regulation of lysosome exocytosis and cancer cell invasion and this has previously been reported in patient cohorts of prostate cancer." (PMID 39217195, 2024). "Western blotting of androgen receptor (AR)-proficient and -deficient prostate lines confirmed upregulation of ARF6 and IQSEC1 protein expression in metastatic prostate cancer cell lines (LNCaP, VCaP, DU145, PC3)." (PMID 33712589, 2021). "Forty-eight hours after transfection, the expression levels of Arf6 mRNA and protein in prostate cancer cells were detected by real-time PCR and Western blot respectively." (PMID 32822124, 2020). "In this stud, downregulation of Arf6 expression by siRNA interference inhibited prostate cancer cell movement, migration and invasion." (PMID 32822124, 2020). "To explore the role of Arf6 in prostate cancer cell proliferation, we used siRNA to downregulate endogenous Arf6 expression in androgen-independent prostate cancer cells." (PMID 32822124, 2020). "The proliferative capacity after Arf6 downregulation was significantly lower than that of the control group, suggesting that Arf6 played a key role in the proliferation of prostate cancer cells." (PMID 32822124, 2020). "siRNA interference inhibited expressions of endogenous Arf6 mRNA and protein in prostate cancer cells." (PMID 32822124, 2020). "In summary, downregulating endogenous Arf6 expression in androgen-independent prostate cancer cells by siRNA interference can significantly reduce their proliferation, migration and invasion." (PMID 32822124, 2020). "Collectively, downregulating Arf6 expression in prostate cancer cells effectively suppressed their migration and invasion." (PMID 32822124, 2020). "Our data supports TSPAN1 as an androgen-driven contributor to prostate cancer cell survival and motility, which can control the expression of the mesenchymal proteins Slug and ARF6." (PMID 28701765, 2017). "Arf6 expression is significantly elevated in prostate cancer clinical samples and it regulates ErbB3 nuclear localization in prostate cancer cells." (PMID 28830537, 2017). "Immunohistochemical staining for ARF6 was performed on a prostate cancer tissue microarray with patient matched normal specimens." (PMID 26185744, 2015). "Hence, downregulating Arf6 modulated the migration and invasion of prostate cancer cells possibly through the downregulation of p-ERK1/2." (PMID 32822124, 2020). "The aim of this study was to provide an experimental basis for revealing the roles of Arf6 gene in the proliferation, invasion, and metastasis of prostate cancer cells through RNA interference, and to design eligible therapies for metastatic prostate cancer using Arf6 as a target." (PMID 32822124, 2020). "The inhibitory effects of Arf6 downregulation on the migration and invasion of prostate cancer cells may be related to the decrease of Rac1 expression." (PMID 32822124, 2020). "Downregulating Arf6 expression can inhibit the proliferation, migration and invasion of prostate cancer cells in vitro, which may be related to ERK1/2 phosphorylation and Rac1 downregulation." (PMID 32822124, 2020). "To study whether the inhibitory effects of Arf6 downregulation on the proliferation, invasion, and migration of prostate cancer cells were related to Rac1, we detected Rac1 protein expression." (PMID 32822124, 2020).
prostate carcinoma (continued). "Therefore, downregulating Arf6 expression in prostate cancer cells effectively inhibited their migration." (PMID 32822124, 2020). "Besides, we used Matrigel with components similar to human extracellular matrix protein, and further coated Transwell chambers with Matrigel to assess the effects of downregulation of Arf6 expression in prostate cancer cells on their invasion." (PMID 32822124, 2020). "Importantly, interrogation of publicly available prostate cancer expression datasets demonstrates that ARF6 mRNA levels are higher in prostate cancer compared with benign tissue." (PMID 26861306, 2016). "In this study, after Arf6 was downregulated, both the cell proliferative capacity and Rac1 expression reduced, indicating that the molecular mechanism by which prostate cancer cell proliferation was suppressed by Arf6 downregulation may be the downregulation of Rac1 expression." (PMID 32822124, 2020). "This group then reported that oncosomes larger than 1 μm could be selectively sorted by flow cytometry in human prostate cancer tissues and in the circulation of mice with metastatic disease and contained MMPs, RNA, caveolin-1, and the GTPase ADP-ribosylation factor 6 (ARF6)." (PMID 32150875, 2020). "We reported that in prostate cancer cells, the small GTPases ARF5 and ARF6 are required to maintain invasive protrusion formation in 3D culture." (PMID 37577760, 2023). "In this study, after Arf6 expression was downregulated, the phosphorylation of ERK1/2 in prostate cancer cells was significantly suppressed." (PMID 32822124, 2020). "We reported a similar function of ARF6 regulating protrusion maturation rather than initiation in conjunction with the ARF GEF protein IQSEC1 in invading 3D cultures of prostate cancer cells (PC3)." (PMID 37577760, 2023). "Therefore, Arf6 regulated prostate cancer cell proliferation probably not via the PI3 K/AKT signaling pathway." (PMID 32822124, 2020). "The expression levels of AKT and p-AKT proteins in negative control, normal control and siRNA groups are not significantly different, suggesting that Arf6 downregulation suppressed the proliferation of prostate cancer cells not via the PI3K/AKT signaling pathway." (PMID 32822124, 2020).
glioma (8 papers, 2012 to 2025). A benign or malignant brain and spinal cord tumor that arises from glial cells (astrocytes, oligodendrocytes, ependymal cells). "Increase of Arf6 expression can promote glioma cell proliferation, which is associated with the activation of PI3K/AKT signaling pathway." (PMID 32822124, 2020). "Moreover, the regulation of glioma cell invasion has been associated with ARF6, which can form a complex with Rac1 and IQGAP1 suggesting a potential link between prominin-1, ARF6 and their interactors in distinct but interconnected processes such as cell migration and EV release." (PMID 39881297, 2025). "Recently, a potential role for Arf1 in glioblastoma progression was suggested, and over-expression of Arf6 was shown to enhance glioma cell migration both in vitro and in vivo." (PMID 30909495, 2019). "ARF6 expression is altered in breast, glioma and lung cancers." (PMID 35143561, 2022). "Oesophageal, cervix, and lymphoid cancers showed significant upregulation of ARF6 mRNA expression in this study, therefore the discussed roles of ARF6 in glioma may be pertinent to these cancers." (PMID 35143561, 2022). "Although glioma tissue was not included in this study, it has been previously used to correlate increased ARF6 expression with high-grade tumour tissues and cell lines." (PMID 35143561, 2022). "In addition, Arf6 is also found to form complexes with Rac1 and IQGAP1 in glioma cells upon HGF stimulation, and IQGAP1 is essential for Arf6-induced Rac1 activation and cell migration." (PMID 22701712, 2012).
lung carcinoma (8 papers, 2017 to 2023). "We focused on lung cancer cell lines because Arf6 knockdown potently inhibited growth in these cancer cells." (PMID 28281543, 2017). "Arf6 RNAi efficiently knocked down Arf6 protein levels and reduced Gli1 levels in lung cancer cells." (PMID 28281543, 2017). "Upregulation of Arf1, Arf4, and Arf6 were found in breast, gastric, prostate, or lung cancer." (PMID 37182141, 2023). "In colon and lung cancer cells, ARL4C promotes cell proliferation through ARF6, RAC, RHO, and YAP/TAZ." (PMID 34590580, 2021).
colon cancer (7 papers, 2017 to 2024). "We knocked down Arf6 in various lung and colon cancer cell lines with oncogenic Ras mutations." (PMID 28281543, 2017). "Furthermore, zelenirstat inhibits the myristoylation of ADP-ribosylation factor 6 (ARF6) in cultured colon cancer cells, and triggers ARF6 degradation (Pacylex, data on file)." (PMID 38837078, 2024). "Moreover, ARF6 gene expression was substantially increased in oesophageal and lymphoid cancers whereas it was insignificantly decreased in colon cancer." (PMID 35143561, 2022). "In colon cancer cells, ACAP2, a downstream effector of Rab35, and also GTPase activating proteins (GAP) of ARF6, inhibits ARF6 and thus inhibits epithelial-mesenchymal transition (EMT) of tumor cells." (PMID 30524285, 2018).
lung adenocarcinoma (6 papers, 2019 to 2023). A carcinoma that arises from the lung and is characterized by the presence of malignant glandular epithelial cells. "In lung adenocarcinoma, the combined expression of ARF6, its GEF BRAG2/GEP100 and EGFR is associated with decreased patient survival." (PMID 32426352, 2020). "Clinically, ARF6 expression and activation of its downstream signaling pathways was determined and associated with poor overall survival of breast, lung adenocarcinoma, pancreatic ductal adenocarcinoma and head and neck cancer patients." (PMID 32426352, 2020). "Since we observed that AXL and CNK2 also stimulate ARF6 activity in LN-229 (glioblastoma) and A549 (lung adenocarcinoma) cells, this strongly suggests that the AXL-CNK2-ARF6 axis is conserved across multiple cancer cell types." (PMID 37322019, 2023). "In lung adenocarcinoma, the co-high expression of ARF6, GEP100 and p-EGFR obviously predicts a bad prognosis." (PMID 37716993, 2023). "In lung adenocarcinoma, the pathway involving EGFR, ARF6 and ASAP1 was reported to be associated with reduced patient survival." (PMID 32426352, 2020).
Sepsis (6 papers, 2017 to 2025). Sepsis is defined as life-threatening organ dysfunction caused by a dysregulated host response to infection. "The excess vascular leak seen in bacterial LPS-triggered sepsis is caused by the activation of ARF6." (PMID 36982738, 2023). "COVID-19 causes leaky vasculature like in LPS-induced sepsis and, therefore, we assessed whether ARF6 activation is altered in the RBD-treated cells." (PMID 36982738, 2023). "From a therapeutic standpoint, most studies on Arf6 have focused on decreasing aberrantly high Arf6 activity in models of cancer, diabetic retinopathy, sepsis, and neurodegeneration 30,37,58–63." (PMID 41509243, 2025). "For sepsis, studies are exploring how pEVs contribute to inflammation and renal injury, with an emphasis on potential therapeutic targets like ARF6." (PMID 39200314, 2024). "In summary, increased platelet-derived EVs during sepsis aggravated septic AKI through the ARF6 release to promote inflammation, apoptosis, and oxidative stress." (PMID 37928258, 2023). "Arf6 activation contributes to sepsis by promoting vascular leakage through excessive internalization of VE-cadherins and additionally interacts directly with exocyst components." (PMID 28945820, 2017). "This suggests that targeting ARF6 could offer a therapeutic approach to mitigate sepsis-related kidney injury." (PMID 39200314, 2024). "Given the negative regulation of Rab11 by Arf6 in flies and its known role in compromising barrier function in the mammalian vasculature during sepsis, we tested whether inhibitors of this pathway might antagonize the effects of EF." (PMID 28945820, 2017). "Moreover, the ARF6 activation leads to an unstable and leaky vasculature in LPS-induced sepsis." (PMID 36982738, 2023). "Importantly, Arf6 plays a role during sepsis to mediate acute VEGF-induced vascular permeability." (PMID 28945820, 2017).
triple-negative breast carcinoma (6 papers, 2016 to 2024). An invasive breast carcinoma which is negative for expression of estrogen receptor (ER), progesterone receptor (PR), and human epidermal growth factor receptor 2 (HER2). "We used MDA-MB-231 cells, a triple-negative breast cancer cell line derived from basal-like tumors with increased Ras, MAPK, and ARF6 activities." (PMID 34344896, 2021).
breast tumor (5 papers, 2015 to 2022). "In this study we used a gain of function approach to mimic up-regulation of ARF6 activity reported in breast tumor cells and to unravel the mechanism through which ARF6 controls cancer cell migration." (PMID 25799492, 2015).
colorectal cancer (5 papers, 2020 to 2025). A primary or metastatic malignant neoplasm that affects the colon or rectum. "Loss of Pals1 in colorectal cancer cells results in increased Arf6 and Rac1 activity, enhanced cell migration and invasion in vitro and increased metastasis of transplanted tumor cells in mice." (PMID 33941200, 2021). "We have recently shown that downregulation of the tight junction adapter protein Pals1 in colorectal cancer cells results in an increase of cell migration, invasion, and metastasis due to the enhanced activation of Arf6 and Rac1." (PMID 36494580, 2023). "Taken together, we concluded from these experiments that Pals1 functions in redundancy with SMAP1 to control the levels of active Arf6 and thus Rac1-mediated cell migration in colorectal cancer cells." (PMID 36494580, 2023). "Taken together, we identified a redundancy between SMAP1 and Pals1 in the regulation of activation of Arf6/Rac1, thereby controlling cell migration, invasion, and metastasis of colorectal cancer cells." (PMID 36494580, 2023). "Recently, we revealed a new function of the polarity regulator Pals1 in controlling cell motility of colorectal cancer cells by inhibiting Arf6, which in its turn controls Rac1-dependent lamellipodia formation and tumor cell migration/invasion." (PMID 36494580, 2023). "Overall, the current results provide evidence that AR decoction inhibits the expression of ARF6 and N-Cadnerin in colorectal cancer cells by inhibiting Wnt5/β-catenin." (PMID 34991661, 2022). "In a previous study, we showed that Pals1 binds and inhibits Arf6 in colorectal cancer cells." (PMID 36494580, 2023). "Moreover, inhibition of Arf6 reduces cell migration of Pals1/SMAP1-double deficient cancer cells and might be considered as a future therapeutic approach for a subset of colorectal cancer patients." (PMID 36494580, 2023). "One possibility to explain the different migration behavior of HCT116 and other colorectal cancer cell lines would be that in HCT116 cells, Arf6 is more sensitive towards the regulatory function of Pals1." (PMID 36494580, 2023). "However, we now found that deletion of Pals1 in other colorectal cancer cell lines did not result in enhanced Arf6/Rac1-dependent cell migration." (PMID 36494580, 2023). "Notably, deletion of Pals1 in three other colorectal cancer cell lines (Caco-2, DLD1 and RKO) alone does not increase cell migration or Arf6/Rac1 activity, due to the expression of the Arf6-specific GAP SMAP1." (PMID 36494580, 2023).
glioblastoma (5 papers, 2012 to 2024). The most malignant astrocytic tumor (WHO grade IV). "This idea is consistent with the report showing that SP1 is required for the EGF-induced expression of Arf6 mRNA in the human glioblastoma cell line U87 cells." (PMID 28429746, 2017). "A recent study has found that Arf6 is required for EGF-induced glioblastoma cell proliferation via the activation of PI3K and ERK signaling." (PMID 22701712, 2012).
ovarian carcinoma (5 papers, 2013 to 2023). A malignant neoplasm originating from the surface ovarian epithelium. "Our approach therefore uncovers an ARF6 vulnerability upon PTEN loss in collective cancer cell behaviour in ovarian cancer." (PMID 37577760, 2023). "Levels of this ARF6 module predict clinical outcome in ovarian cancer patients." (PMID 37577760, 2023). "Moreover, c-Src-mediated inhibition of Arf6 activity was not limited to fibroblasts, as a similar response was observed in A2780 ovarian carcinoma cells." (PMID 23453597, 2013). "In this regard, the findings reported in this study will assist further investigation of ARF6 GEF activity-dependent and -independent roles of EFA6R in ovarian cancer." (PMID 25296758, 2014). "Together, these data indicate that AGAP1 is required for invasion in Pten‐null cells and that ovarian cancer patients with high ARF6 and AGAP1 levels, irrespective of the isoform of the AGAP1, have a poor clinical outlook." (PMID 37577760, 2023).
renal carcinoma (5 papers, 2016 to 2025). A carcinoma arising from the epithelium of the renal parenchyma or the renal pelvis. "While other findings indicate that EFA6B promotes the invasion and metastasis of renal cancer through ARF6 activation mediated by Lysophosphatidic acid." (PMID 35140331, 2022). "Here, the authors show that in renal cancer cells, lysosphosphatidic acid does not utilize the RhoA pathway but specifically activates the Arf6 mesenchymal pathway via its GPCRs and EFA6 to promote invasion, metastasis and drug resistance." (PMID 26854204, 2016).
uveal melanoma (5 papers, 2017 to 2022). A melanoma derived from melanocytes of the uveal tract. "It has been reported that GNAQ and ARF6 control the subcellular localization and transactivation of β-catenin in uveal melanoma cells." (PMID 31320995, 2019). "Liver metastasis is a common site for solid tumor metastasis, including lung, breast, pancreatic, and uveal melanoma, and ARF6 activation might be a common thread, as ARF6 activation has been shown to be an adverse prognostic factor in these common malignancies." (PMID 31320995, 2019). "Finally, Cry61 is an established target of ARF6 in uveal melanoma." (PMID 31320995, 2019). "NAV-2729, which can bind to human ARF6 in the GEF binding region and thus inhibit the interaction of ARF6-GEF, has been used in the treatment of uveal melanoma." (PMID 36091067, 2022). "Inhibition of ARF6, by the ARF6 specific small-molecule inhibitor, NAV-2729, reduces uveal melanoma cell proliferation and tumorigenesis in a mouse model." (PMID 34944815, 2021). "To determine the effect of Tris DBA palladium on ARF6 activation, we performed ARF6-GTP pulldown assays on Mel92.1 and Mel202 uveal melanoma cell lines that had been treated with concentrations of Tris DBA palladium ranging from 1 to 5 μM." (PMID 31320995, 2019). "ARF6 potentiates hepatocyte growth factor/MET signaling, which is a key player in the high rate of hepatic metastasis seen in uveal melanoma." (PMID 31320995, 2019). "Recently, ARF6, a small GTPase, has been found to be a major node in GNAQ mutant uveal melanoma." (PMID 31320995, 2019).